JAG1 (jagged canonical Notch ligand 1)
Diseases named in the same sentence as JAG1 in open-access papers (continued):
Sharing a sentence is not in itself a finding about the gene and the disease.
tumor (continued). "We will first present and describe the mechanisms by which JAG1 exerts its functions in tumor biology, and then discuss its role in selected tumor types for which function and/or clinical relevance have been most extensively reported." (PMID 25309874, 2014). "We demonstrated a role for endothelial Jag1-tumor notch activation in enriching mammary stem cells by several approaches." (PMID 25380486, 2014). "NOTCH1 and JAG1 decreased with increasing tumour stage and became undetectable in several high stage tumours." (PMID 25167871, 2014). "Overall, these data indicate JAG1 as an important inducer of the stem cell phenotype in different cancer types and, importantly, demonstrates that both tumor and stromal JAG1 expression are relevant targets for CSCs." (PMID 25309874, 2014). "This, in conjunction with the relevance demonstrated in different tumor types, suggests JAG1 as an interesting therapeutic target to inhibit tumor cell invasiveness/metastasis." (PMID 25309874, 2014). "JAG1 mRNA and protein are overexpressed in this tumor type, with high expression levels correlating with poor prognosis." (PMID 25309874, 2014). "JAG1 gene silencing in tumor cells reduced viability and sensitized them to taxane treatment both in vitro and in vivo, where it drastically reduced tumor growth." (PMID 25309874, 2014). "Notch ligand jagged-1 (JAG1) is highly expressed in bone metastatic tumor cells and is again activated by bone-derived TGF-β during osteolytic bone metastasis." (PMID 25147739, 2014). "One of the Notch ligands, Jagged1 (JAG1), is overexpressed in many cancer types, and plays an important role in several aspects of tumor biology." (PMID 25309874, 2014). "In conclusion, targeting JAG1 will provide a new approach to act on multiple aspects of tumor biology, and represents a promising new strategy in developing novel anti-tumor therapies." (PMID 25309874, 2014). "Our in vivo findings further determined the role of endothelial Jag1 in enhancing tumor development not only by tumor cells but also by EC-enriched mammary stem cells." (PMID 25380486, 2014). "Apart from inducing Notch activation from cancer cells themselves, JAG1 expressed by stromal cell also plays an important role in supporting cancer cell survival and tumor growth in hematological malignancies." (PMID 25309874, 2014). "In this review, we summarize what has been discovered about the contribution of JAG1 to tumor biology to date, and discuss the evidence supporting JAG1 as a valid target for cancer therapy." (PMID 25309874, 2014). "For example, while Notch1 is often oncogenic when expressed by cancer cells, Notch3 expressed by perivascular cells plays a major role in JAG1-mediated vascular function, and it is also important in Treg induction and expansion in the tumor microenvironment." (PMID 25309874, 2014). "To confirm if this ligand plays a role in activating tumor notch pathway, we silenced its expression on E4-ECs using shRNA against Jag1." (PMID 25380486, 2014). "This article gives an overview of JAG1 and its role in tumor biology, and its potential as a therapeutic target." (PMID 25309874, 2014). "JAG1 activity was indispensable for tumor maintenance as dominant negative JAG1 and RNA interference reduced cell line tumorigenicity in vitro." (PMID 25309874, 2014). "The induction and expansion of Treg cells in the tumor microenvironment involves crosstalk between tumor cells and dendritic cells, in which Notch signaling, and in particular JAG1-induced Notch activation, plays an important role." (PMID 25309874, 2014). "Combination treatment of SKOV3Trip2-derived tumors with human and mouse specific Jag1 siRNAs and docetaxel led to the highest decrease in tumor weight, compared with the siRNAs alone or docetaxel alone." (PMID 25366565, 2014). "Either siRNA alone reduced tumor growth, and the combination of mouse and human Jag1 siRNAs showed a synergistic effect in tumors derived from both cell lines." (PMID 25366565, 2014).
tumor (continued). "This tumor-expressed JAG1 then stimulates endothelial cell sprouting, promoting angiogenesis and tumor growth in a mouse xenograft model." (PMID 25309874, 2014). "It is well established that the Notch pathway, and in particular JAG1-induced Notch activation, plays important roles in tumor biology, affecting both cancer cells and multiple components of the neoplastic microenvironment (e.g., vasculature and immune cells)." (PMID 25309874, 2014). "Furthermore, in HCC cells and mouse hepatocytes, upregulation of JAG1 activates Notch signaling, promoting cell and tumor proliferation." (PMID 40796539, 2025). "This indicated that JAG1 knockdown could hinder the activity and proliferation of tumor cells while slowing down tumor growth." (PMID 39744570, 2025). "The test results showed that knockdown of JAG1 could indeed inhibit tumor invasion as well as migration, and could inhibit tumor progression." (PMID 39744570, 2025). "Notably, JAG1 has been reported to signal to tumor cells to promote angiogenesis and tumor growth via the mitogen-activated protein kinase (MAPK) pathway." (PMID 40952540, 2025). "Additionally, experimental results demonstrate that silencing JAG1 yielded a significant decrease in tumor cell proliferation in LGG cell lines, and JAG1 potentially influences PD-L1 in LGG by regulating the PI3K/AKT signaling pathway." (PMID 38474320, 2024). "The results show that tumor grade (grade 2 versus grade 3) was significantly associated with ADS-stimulated increases in JAG1 protein in MDA-MB-231, but not MDA-MB-436 cells." (PMID 39408921, 2024). "Consequently, tumor growth in a murine lung tumor model was increased when JAG1 overexpressing tumor cells were used and hampered in galectin-3 knockout mice." (PMID 38990363, 2024). "Moreover, the potential of JAG1 as a target for tumor angiogenesis was demonstrated, where it was found that an increase in endothelial JAG1 expression led to an increase in tumor size." (PMID 37781534, 2023). "Finally, we validated that patient with high JAG1 expression had a low immune-infiltrating tumor microenvironment through single-cell transcriptomic data." (PMID 36923423, 2023). "Interestingly, CAF states 2 and 3 (inflammatory/adipogenic CAFs) were shown to mediate crosstalks with tumor endothelial cells notably via NOTCH1/2/3_JAG1/2/DLL4 pathways reiterating the role of NOTCH signaling in CAF-mediated angiogenesis." (PMID 38269089, 2023). "Jagged1 (JAG1) is a Notch ligand that correlates with tumor progression." (PMID 38092725, 2023). "Additionally, both the JAG1 and DLL4 levels were associated with poor differentiation, invasion, regional lymph node metastasis, a maximum tumor size > 5 cm, TNM III/IV disease, and survival." (PMID 35673567, 2022). "In summary, NOTCH signaling mainly promotes the immune-suppressive and tumor-promoting functions of MDSCs; thus, targeting JAG1/2 might be a promising strategy." (PMID 35332121, 2022). "The JAG1-Notch pathway facilitates tumor metastasis via various carcinogenic mechanisms." (PMID 36539520, 2022). "A novel class of Notch inhibitors that block JAG1 has been shown to limit tumour angiogenesis." (PMID 35349480, 2022). "The balance of DLL4 and JAG1 endothelial expression is important for tumor vasculature generation." (PMID 35332121, 2022). "Moreover, endothelial JAG1, released by tumor cells, can also enhance tumor neoangiogenesis, increasing tumor vessel density and branching by modulating VEGFR2 expression." (PMID 35745656, 2022). "In addition, JAG1 promotes cancer stem cell self-renewal, tumor cell proliferation, drug resistance and survival." (PMID 35401837, 2022). "Sequential blockade of HER2 followed by JAG1 or Notch could be more effective than simultaneous blockade to prevent drug resistance and tumor progression." (PMID 35682974, 2022).
tumor (continued). "In basal-like subtypes of BC, high JAG1 expression induced by the NF-KB pathway could activate the Notch pathway, and then accelerate self-renewal and replication of tumor stem cells." (PMID 36539520, 2022). "Indeed, we show that GSI compounds trigger Jag1-ICD release, which promotes cellular growth and EMT processes, functioning as tumor-promoting agents in CRC cells overexpressing Jagged1." (PMID 35847908, 2022). "Furthermore, the BBB model showed that JAG1 upregulation significantly increased tumor cell adhesion and penetration into the BBB." (PMID 36539520, 2022). "HOTAIR serves as tumor promoter, increasing Notch1 and JAG1 expressions in retinoblastoma." (PMID 36229883, 2022). "Additionally, a BBB model revealed that JAG1 knockdown significantly weakened the tumor cell adhesion and penetration into the BBB." (PMID 36539520, 2022). "JAG1, Notch1 and Slug expression correlate in patient tumour samples." (PMID 34295896, 2021). "In both data sets, JAG1 expression is significantly higher in tumors than in non-tumor tissues." (PMID 33268505, 2021). "Recent studies in OS prove that JAG1 enhanced tumor growth and metastasis." (PMID 34421997, 2021). "Additionally, in vivo experiments also manifest that circ_0084582 aggravates tumor growth by upregulating JAG1." (PMID 34421997, 2021). "Finally, we disclosed that KDM4D directly interacts with JAG1 promoter and advances tumor angiogenesis by upregulating VEGFR-3 and antagonizing notch signaling." (PMID 34667158, 2021). "Interestingly, Jag1 is overexpressed in the early stages of tumor growth, while it remains silent in homeostatic conditions." (PMID 32796631, 2020). "Previous studies have shown that JAG1 regulated tumor progression, including NSCLC." (PMID 32377169, 2020). "MicroRNA-26b and microRNA-377-3p could suppress tumor development and invasion through sponging JAG1/Notch signaling." (PMID 33329315, 2020). "In addition, the most highly expressed Notch3 ligand in OC cells and mesothelial cells in the peritoneum is Jagged 1 (Jag1), which has been shown to promote OC cell proliferation and adhesion, suggesting a role for the Jag1/Notch3 axis in tumor dissemination." (PMID 32512891, 2020). "JAG1 is expressed in the tumor microenvironment by peritoneal mesothelium and tumor-associated endothelium and loss of JAG1 in adjacent cells reduces tumor cell adhesion and growth, suggesting that microenvironmental activation of Notch3 is critical in tumor progression." (PMID 32525899, 2020). "Moreover, monomeric soluble JAG1 treatment reduced T-regulatory cells and improved anti-tumor immune responses by decreasing the expression of PD-1 on CD8+Tem cells." (PMID 30940183, 2019). "The upregulated JAG1 expression may interact with aggressive tumor behaviour, tumor progression and expansion, predicting as a potential candidate for biomarker of disease progression." (PMID 29921897, 2018). "This is revolutionary, since we could treat patients with JAG1-blocking antibody targeting exclusively the tumor cells and avoiding the strong sides effects in the normal gut of FAP patients." (PMID 30065304, 2018). "The expression level of JAG1 was up‐regulated in the tumor size larger than 3 cm group." (PMID 29464926, 2018). "Our results indicated that GZZSZTW significantly increased the expression levels of multiple genes involved in promoting cell proliferation, most of which are highly expressed in tumor cells, such as Tnfaip2, Chi3l1, Tnf, Pfkfb3, Sox8, Jag1, Mafb, Pla2g7, Hnrnpa1, and E2f3." (PMID 30275866, 2018). "Because Notch signaling plays a role in angiogenesis, there is also the possibility that macrophage JAG1 may affect endothelial cells directly, affecting cell junctions and blood vessel permeability, potentially allowing tumor cells to enter the bloodstream." (PMID 29636067, 2018).
tumor (continued). "Therefore, cancer cells expressing JAG1 plays pivotal roles in two manners: (i) JAG1 acts as a ligand and complexed with its receptor activating neighboring cells of a tumor in a juxtacrine way." (PMID 29921897, 2018). "Different tumour cell lines might differentially express other NOTCH ligands (in addition to JAG1) or other NOTCH pathway modulators, conferring additional complexity." (PMID 29743479, 2018). "Past studies have focused on characterizing ErbB3 expression of tumor cells, but our experiments suggest that JAG1 and ErbB3 expression on macrophages may also play an important role." (PMID 29636067, 2018). "(ii) The ICD (intracellular domain) of JAG1 may initiate Notch pathway and propagate tumor cell growth, leading to deregulation of JAG1." (PMID 29921897, 2018). "Upregulation of JAG1 is accompanied by increased Notch and CNTN1 expression indicating that the tumor cells themselves were, at least in part, target of the increased Jagged 1 signaling as there obviously were interactions between tumor cells via Jagged 1 / Notch." (PMID 29432466, 2018). "Importantly, anti-DLL4 antibody blocked the effect of JAG1 on tumour growth and increased vessel branching in vivo." (PMID 28445154, 2017). "Although the importance of gal-3 in angiogenesis is already widely appreciated, we now point to a novel regulatory mechanism by which tumor-secreted gal-3 increases tip cell formation and sprouting angiogenesis because of its ability to upregulate JAG1/Notch-1 signaling in endothelial cells." (PMID 28533486, 2017). "In addition, bone resorption can be promoted by the Notch signaling pathway, which results in IL‐6 secretion upon binding of tumor‐derived JAGGED‐1 (JAG‐1) to osteoblasts." (PMID 28017284, 2017). "To confirm in vivo that tumour-derived expression of Jag-1 could increase angiogenesis, we established graft of LLC1 overexpressing Jag-1." (PMID 28719575, 2017). "Indeed, an increase in sprouting angiogenesis has been demonstrated in the retina of mice with JAG1 gain-of-function and tumour models with such mice." (PMID 28445154, 2017). "Both DLL4 and JAG1 increase vessel perfusion and thus reduce necrosis and enhance tumour growth." (PMID 28445154, 2017). "The analysis of the gene expression showed JAG1 to be one of 17 cytokine/ligand genes overexpressed in bone metastasis in comparison to liver, brain and lung metastasis, implying a potential organ-specific function for tumor-derived JAG1 in metastatic colonization of the bone." (PMID 29104587, 2017). "On the other hand, recombinant ligands such as Dll1, Dll4, and JAG1 have been reported to activate Notch signaling in various cell types, including intestinal organoids and tumor spheroids." (PMID 28455349, 2017). "Notably, expression of endogenous JAG1 intensified in tumour and stromal cells of mDLL4-tumour compared to that of EV-tumour (II versus I)." (PMID 28445154, 2017). "Therefore, we investigated different effects of DLL4 and JAG1 on in vitro angiogenesis, on xenograft tumour growth and vasculature, and on tumour response to anti-VEGF therapy." (PMID 28445154, 2017). "Perhaps, expression of DLL4 and/or JAG1 in different cell types such as ECs, tumour cells or other stromal cells might have different effects due to the lateral inhibition." (PMID 28445154, 2017). "In addition, Delta-like 4 (DLL4) and Jagged-1(JAG1) were reported to be involved in the process of tumor angiogenesis." (PMID 27557513, 2016). "Furthermore, tumours from AKT/Jag1 mice exhibited extensive desmoplastic reaction, an important feature of human ICC." (PMID 27918553, 2016). "NOTCH3(+)CAFs may promote sprouting of tumor endothelial cells by a molecular mechanism similar to that of the DLL4/NOTCH1 pathway and stabilize the newly formed tumor vessels through JAG1/NOTCH3 interactions between endothelial cells and CAFs." (PMID 27124156, 2016).
tumor (continued). "In both tumor types, introduction of JAG1 into the cancer cells increased overall Notch signaling levels in the culture, but we still observed heterogeneity in ligand levels, which likely facilitated this overall pathway induction and made it difficult to separate signal sending and receiving cells." (PMID 25557173, 2015). "In contrast, endothelial Jag1 loss-of-function delayed the growing rate of LLC subcutaneous transplants and inhibited the development of prostate lesions in TRAMP mice, by decreasing the density and branching of the tumor neo-vasculature." (PMID 26213336, 2015). "Accordingly, JAG1 knockdown leads to reduced Notch signaling activity that is accompanied by cell growth inhibition, cell cycle arrest, migration, and invasion inhibition, as well as tumor growth suppression." (PMID 25309874, 2014). "Furthermore, JAG1 can increase tumor migratory and invasive behavior by inducing the urokinase-type plasminogen activator (uPA), a well-known marker of recurrence and metastasis." (PMID 25309874, 2014). "In addition, while in the context of cancer, DLL4 mainly functions in the vasculature, JAG1 has roles in vasculature, immunosuppressive Treg cells, and the tumor/stem cells." (PMID 25309874, 2014). "In several cancer types, JAG1 induces tumor cell growth and promotes cell cycle progression." (PMID 25309874, 2014). "Functionally, in vitro JAG1 knockdown inhibits tumor cell growth inducing cell cycle arrest." (PMID 25309874, 2014). "A soluble JAG1 extracellular domain, generated by ADAM17-mediated proteolytic cleavage, has also been implicated in mediating paracrine Notch signaling between endothelial cells and tumor cells, thus enabling Notch activation in more distant cells." (PMID 25309874, 2014). "In addition, JAG1 can indirectly affect cancer by influencing tumor microenvironment components such as tumor vasculature and immune cell infiltration." (PMID 25309874, 2014). "Therefore, we speculate that targeting JAG1 may effectively inhibit tumor progression, thereby providing better prognosis for NPC patients." (PMID 39744570, 2025). "Additionally, the expression of JAG1 in tumor tissues is elevated compared to normal brain tissues." (PMID 38022677, 2023). "In addition, the researchers found that soluble monomeric JAG1 signaling significantly reduced the immunosuppressive function of Treg cells and increased anti-tumor immunity, further highlighting the crucial role of Notch signaling and its related ligands in immunity." (PMID 38022677, 2023). "In addition, immune cells may drive Notch signaling at the edge of the tumor, as for breast cancers, where the stimulation of JAG1/NOTCH interactions by cytokine like IL-6 triggers a partial mesenchymal phenotype and an increase in stem-like characteristics." (PMID 37860822, 2023). "Thus, both Jag1 and Lkb1 may function as a tumor suppressor in the pathogenesis of pancreatic cystic neoplasm." (PMID 33268505, 2021). "Finally, loss of Notch1 in tumor cells did not affect the protein expression of Notch2, Jag1, and BEC marker Sox9 as well as mRNA levels of Notch targets, including Hes5 and Hey2." (PMID 29545603, 2018). "Therefore, circumstances that lead to the up-regulation of gal-3 in the tumor microenvironment may influence JAG1 activity both in cancer and endothelial cells." (PMID 28533486, 2017). "In addition, inhibiting NOTCH2 or Jag1 dramatically reduces tumour burden and growth." (PMID 25985737, 2015). "This, in addition to the facts that JAG1 is often upregulated in tumor cells (although generally not mutated in cancer), and that ligand-induced activation is required even in the presence of some Notch receptor mutations, makes it a particularly attractive target for therapy." (PMID 25309874, 2014). "Likewise, JAG1 has also been involved in CSC biology in other tumor types." (PMID 25309874, 2014). "Hence, the effective contributionof normal cell expressed JAG1 on tumour development is unclear." (PMID 21479216, 2011).